CRP (C-reactive protein)
Diseases named in the same sentence as CRP in open-access papers (continued):
Sharing a sentence is not in itself a finding about the gene and the disease.
infection (continued). "C-reactive protein has biological relevance since its serum levels increase within six hours in response to infection and/or inflammation, and its circulating levels decrease rapidly when the stimulus is removed." (PMID 29267535, 2018). "One study about clinical diagnosis revealed a substantial proportion of the patients in the CV-A2 infection groups noted with an elevated serum C-reactive protein level, which was higher than in the EV-A71 and CV-A16 infected patients." (PMID 30235342, 2018). "The patient had a septic revision in the past, showed loosening signs in the preoperative X-ray, had clinical symptoms of an infection, and had an elevated CRP >1 mg/dl." (PMID 30035117, 2018). "With the exception of NO stimulation by estrogen in unactivated macrophages treated with nCRP, the predominant reduction of CRP-induced NO levels by estrogen supports evidence that estrogen reduces the inflammatory response following injury and infection." (PMID 30013561, 2018). "This is an important finding since CRP is often used in clinical practice as an aid to diagnose and monitor the course of an infection." (PMID 30071826, 2018). "Microbiological sampling should always be accompanied by histopathological analysis, and possibly additional markers like α-defensin or C-reactive protein, allowing for complete assessment of possible infection." (PMID 29947288, 2018). "C-reactive protein (CRP) is an acute-phase protein produced by hepatocytes and is a reliable serum marker of infection, tissue destruction, necrosis and systemic inflammation." (PMID 30202676, 2018). "Acute-phase markers such as C-reactive protein (CRP) increase over 1,000-folds during inflammation induced by infection, trauma, surgery, burns, tissue infarction, various immunologically mediated, and advanced cancer." (PMID 30356710, 2018). "Procalcitonin rises more rapidly than C-reactive protein in case of infection and decline more quickly in terms of recovery." (PMID 30675399, 2018). "In the following weeks (day 5–14), the patient showed signs of improvement in infection control with decreasing C-reactive protein (CRP) and was afebrile, however the left lung remained deflated." (PMID 30064365, 2018). "The combination of these two cytokines with CRP can enable the continuous detection of inflammatory phenomena resulting from infection." (PMID 30542642, 2018). "In patients with an infection, the respective AUCs of suPAR on the day of infection were higher than those of CRP values." (PMID 30071826, 2018). "Infection persistence is assessed by means of clinical examination and blood infection markers such as the C-reactive protein (CRP)." (PMID 30009171, 2018). "For dynamic changes of laboratory data, values of white blood cell (WBC) count, neutrophilic granulocyte percentage (Neu%), C-reactive protein (CRP), and erythrocyte sedimentation rate (ESR) were all high in the initial infection (caused by strain XNO62)." (PMID 30013523, 2018). "WBC and CRP increase slowly after bacterial infection or inflammatory reactions occur, which makes it easy to delay the diagnosis time and allow the infection to worsen." (PMID 29968788, 2018). "Different inflammatory markers, such as CRP, D-dimer, and pro-inflammatory cytokines, are increased during the course of the infection." (PMID 29963050, 2018). "Secondary objectives were to describe the extent to which CRP and procalcitonin concentrations differed between the three infections and to determine optimal concentration cut-offs for discriminating those with and without each target infection." (PMID 30107791, 2018). "C-reactive protein (CRP) is a very important biomarker of infection and inflammation for a number of diseases." (PMID 29597295, 2018). "The combination of albumin and CRP measurements resulted in the most improved predictive power for cardiovascular death in patients on HD and for infection-related death in patients on PD." (PMID 29494637, 2018).
infection (continued). "In the context of infection, inflammasome-associated IL-1β shifts IL-6-dependent synthesis of APP to those involved in pathogen defense, including hepcidin, C-reactive protein, serum amyloid P, and serum amyloid A49." (PMID 29891920, 2018). "Other studies, however, have reported that PCT is a better marker for NBI than CRP, with PCT found to have a greater sensitivity and a lower LR- than CRP during initial stages of infection." (PMID 30542642, 2018). "For the diagnosis of any infection, blood samples were taken from the neonate on the first and second day of life and CRP and leukocyte counts were determined." (PMID 29450194, 2018). "By using transgenic mice expressing human CRP, the study found that CRP offered protection against a low dose of Typhimurium and increased resistance to a fatal infection with a low dose of Typhimurium." (PMID 29706967, 2018). "Though the concentrations of PCT and CRP in different infections were different, itis necessary to establish a cut-off value." (PMID 29846409, 2018). "The levels of plasma adipokines (resistin, leptin, adiponectin), and other markers of inflammation (leukocytes, plasma IL-6, CRP) in the acute phase of Puumala hantavirus infection compared to the recovery phase and one year after the infection." (PMID 30517161, 2018). "During the next days, the patient developed an increase in leukocytes (up to 23,000/μL) and in infection parameters (peak C-reactive protein (CRP) 9.35 mg/dl (890.48 nmol/l), peak procalcitonin (PCT) 134 μg/l)." (PMID 30359322, 2018). "CRP is the prototypical acute-phase reactant and an active regulator of the innate immune system; CRP levels increase rapidly in response to infection, inflammation, and tissue injury." (PMID 29725335, 2018). "Because of the original trial design in which all children at risk for serious infection had a POC CRP test, the group of children with known CRP levels was somewhat different from the group of children in which CRP was not tested." (PMID 30354904, 2018). "C-reactive protein levels are known to increase dramatically in response to injury, infection, and inflammation." (PMID 29706967, 2018). "The CRP/albumin ratio has been extensively studied as an independent prognostic marker in patients with infection, malignancy, and other diseases." (PMID 30297655, 2018). "One patient had recurrence of infection after membrane induction, with complications of pain, fever and serological examination suggest C reactive protein increased." (PMID 30344555, 2018). "CRP is increased 24–48 hours after bacterial infection and belongs to the late-onset infection index." (PMID 29968788, 2018). "Even in severely affected patients with extensive infection and exceedingly high CRP levels, the authors nowadays tend towards surgery, if medically feasible." (PMID 29356895, 2018). "Serial CRP monitoring has been found to be valuable for the early diagnosis and monitoring of infections in neutropenic febrile children and has reliably differentiated between bacterial infections and other causes of fever." (PMID 30202676, 2018). "PCT and CRP are new approaches used to guide antibiotic therapy and have beenresearched as markers of infection in serum and pleural fluid." (PMID 29846409, 2018). "There are two distinct isoforms of CRP, nCRP and mCRP, and the nCRP isoform can irreversibly dissociate at sites of inflammation, tissue damage, and infection into five mCRP subunits." (PMID 29706967, 2018). "In CoNS infection episodes, BDL was associated with CRP, indicating the potential use of BDL as a marker of severity of infection." (PMID 29679983, 2018). "CRP levels show a rapid and sensitive change in acute trauma and infection and can reflect the change of inflammatory reaction in an organism." (PMID 29668624, 2018). "Children with infection had higher C-reactive protein at the time of diagnosis (148 vs 112 mg/L, p = 0.04), and 48 hours after IVIG administration (111 vs 59 mg/L, p = 0.003)." (PMID 30332473, 2018).
infection (continued). "CRP levels were significantly higher in the infection persistence group than in the infection eradication group at PR (p < 0.00)." (PMID 29321073, 2018). "Infection was defined, when the neonate had clinical signs and a positive blood culture and/or a CRP value above the cutoff value of 10 mg/l." (PMID 29450194, 2018). "Further studies are needed to expand on these emerging findings and to fully characterize the differential roles that each CRP isoform play at sites of local inflammation and infection." (PMID 29706967, 2018). "Hematology counts for WBC, RBC, CRP, monocytes and eosinophil throughout the course of the disease pointed towards continued infection in the body." (PMID 30210807, 2018). "Some infection index such as C-reactive protein, procalcitonin and Leukocyte count didn’t change significantly as IPA developed." (PMID 29343867, 2018). "The clinical and laboratory markers present in more than 50.0% of patients with line infection were raised white cell count, raised neutrophils, rigors, fever, tachycardia and raised C-reactive protein." (PMID 30568839, 2018). "Logistic regression analysis showed that fever, abdominal pain, elevated absolute neutrophilic count and positive C-reactive protein are independent predictors of ascitic fluid infection." (PMID 30289914, 2018). "C-reactive protein (CRP) is an acute inflammatory protein that increases up to 1,000-fold at sites of infection or inflammation." (PMID 29706967, 2018). "In children, POC CRP testing has proven valuable in ruling out serious infections, but the effect of its use by GPs on the prescription of antibiotics was not known." (PMID 30564733, 2018). "Our results show a similar expression level of CRP and C3 in both mice strains prior to infection, as well as during the following time points post-infection, suggesting a similar capacity to activate the classical complement pathway." (PMID 30333823, 2018). "The levels of PCT and CRP of the three groups were determined respectively; patients in the infection group and non-infection group were determined again after administration of antibacterial drugs for a period of time." (PMID 28811772, 2017). "CRP tends to rise quickly in response to injury or infection and has a half-life of ∼2 d, whereas AGP rises slower but remains elevated with a half-life of ≥5 d." (PMID 28615259, 2017). "The variation in slopes across surveys necessitates further investigations to identify potential modifiers of the ferritin–CRP-AGP relation in particular the examination of differential effects by the type of infection or inflammatory event." (PMID 28615259, 2017). "A classical plasma protein marker of acute phase of inflammation, infection, and tissue damage is CRP." (PMID 29158612, 2017). "The data have shown a clear relationship between presepsin level and CRP, suggesting its sensitivity and validity in evaluation of infection." (PMID 28056845, 2017). "C-reactive protein is a pentameric protein secreted by the liver in response to injury and infection." (PMID 28112148, 2017). "While Hp concentrations remained unchanged throughout the study, CRP increased significantly at eight hours after infection." (PMID 28245826, 2017). "Clinically, the combination of the C-reactive protein level and white blood cell count is commonly used as a basis for determining infection, although there is a lack of solid evidence." (PMID 29201568, 2017). "CRP levels peak at 24 to 48 hours after onset of an infection, which coincide with the care seeking pattern in rural settings of Tanzania where a majority of patients delay to seek hospital care." (PMID 28451028, 2017). "ESR is a non-specific hematological marker routinely used as an indirect parameter of increased acute phase reactants, and CRP is a major acute phase reactant and produced by the liver in response to inflammation, infection, malignancy or tissue damage." (PMID 28623906, 2017).
infection (continued). "Being an exquisitely sensitive marker of systemic inflammation and tissue damage, CRP is very useful in screening for organic disease, monitoring treatment responses, and detecting infection." (PMID 29058588, 2017). "For the biomarkers established in routine diagnostics (CRP, HS-CRP, PCT), the optimized cut-offs resulted in moderate diagnostic power to discriminate between patients with isolated cardiac device pocket infections and healthy controls." (PMID 28264059, 2017). "The levels of PCT and CRP were (1.97±0.13) μg/L and (7.34±2.66) mg/L respectively in the infection group after treatment, which was much lower than the levels before treatment (P<0.05)." (PMID 28811772, 2017). "PCT has so far been shown to be superior to CRP in the diagnosis of infection in the immediate postoperative period in transplant recipients." (PMID 28704503, 2017). "This is in consonance with what is known about CRP in the preterm i.e. that both the baseline level of CRP and the response to infection are lower in premature infants compared to the term new-borns." (PMID 28839172, 2017). "None of the 56 patients (median age 56, 22 men and 34 women), representing patients who had sought medical care for general medical reasons showed any sign of infection and had normal values of C-reactive protein (<10 mg/L)." (PMID 29318041, 2017). "Our study indicates that the Cu/Zn ratio correlates to the CRP levels determined at day 3 as the established biomarker of infection." (PMID 28358335, 2017). "As the golden standard for the surgical treatment of infectious spondylodiscitis, the A+P group also had good infection control with excellent improvement on the CRP level and WBC count (57 ± 6% and 23 ± 16%, respectively) within 2 weeks after surgery." (PMID 29049254, 2017). "The fall in elevated CRP level, in treated animals during 4 days post-infection, indicated recovery vis-a-vis efficacy of the topical ointment." (PMID 28401944, 2017). "Although CRP is an acute-phase protein which increases in response to infection, its prognostic value has been evaluated in various settings." (PMID 28938875, 2017). "The CRP level was found to be elevated in both treated and control animals up to 2 days post-infection." (PMID 28401944, 2017). "In contrast, the CRP and IL-6 levels were under control in the pigs treated with Epi-1 after infection." (PMID 28177877, 2017). "Conversely, in the high–infection-burden countries, the prevalence of an elevated CRP concentration in WRA (median: 17.8%) was lower than that in PSC (median: 37.5%) in data sets that included information on both populations." (PMID 29070567, 2017). "In our previous study, albeit with a small sample size, PCT was shown to be superior to CRP and leukocyte determination in infection diagnosis during the first week after lung transplantation." (PMID 28704503, 2017). "In the comparison of the levels of the cytokines, IL-6, IL-10, and CRP were statistically higher in patients with infection than the post-treatment values." (PMID 28148470, 2017). "CRP was expectedly elevated in the viremic patients of infection (61.0%) but normal in all post-viremic patients." (PMID 29065182, 2017). "PCT and CRP are both proteins produced during a normal physiologic inflammatory response, or during the response to infection." (PMID 29104224, 2017). "C-reactive protein (CRP) is an inflammatory marker which is closely related to the infections and outcomes in orthopaedics." (PMID 28977869, 2017). "CRP is proved to be very useful in diagnosis and functioned as a monitor of infections in orthopaedics." (PMID 28977869, 2017). "C-reactive protein (CRP) is an acute-phase protein that increases rapidly following interleukin-6 secretion by macrophages and T cells following infection, inflammation and cancer." (PMID 28859644, 2017). "One out of three animals with increased CRP concentrations after infection developed neurological disorders." (PMID 28559930, 2017).
infection (continued). "CRP is an acute-phase protein produced by the liver, and it is widely used as an objective marker for detecting tissue damage and infection." (PMID 28278168, 2017). "Higher leukocyte counts and CRP values were found among Salmonella Typhi-infected patients, suggesting a more severe infection." (PMID 28931025, 2017). "Median levels for PCT and CRP levels for each day of follow-up, in ‘Infection’ and ‘primary graft dysfunction (PGD) grade 3’ specifically." (PMID 28704503, 2017). "It is worth stressing that CRP is requested more frequently for infected patients, since it is often a good indicator of infection." (PMID 29216923, 2017). "Serum levels of human CRP increase up to a thousand fold during infection and inflammation, and elevated serum CRP levels are a biomarker for predicting inflammatory diseases." (PMID 28619036, 2017). "C-reactive protein (CRP), previously considered a biomarker of underlying infection or tissue injury, is now also believed to reflect chronic systemic inflammation." (PMID 28687081, 2017). "As expected, infection parameters such as white blood cell count and CRP were slightly elevated in UTI patients." (PMID 29145515, 2017). "CRP is a highly sensitive inflammatory marker that is produced mainly by the liver inresponse to infection, inflammation and trauma." (PMID 28384165, 2017). "Children with a single HMPV infection had a higher peak temperature and higher peak CRP levels, but adjusted for age, these differences also disappeared." (PMID 28095451, 2017). "In WRA in the United States, which is a low–infection-burden country, ID was 7 pps higher when adjusting for CRP alone." (PMID 29070567, 2017). "Patients with single-strain infections had a higher start-of-treatment CRP with improved lung function observed during treatment of the exacerbation." (PMID 29096618, 2017). "CRP also helps the body recognize the presence and severity of infections and is used as an indicator of low-grade inflammation in chronic infections and chronic diseases." (PMID 28571565, 2017). "Comparison of the levels of PCT and CRP between the infection group and non infection group before and after treatment (mean±SD)." (PMID 28811772, 2017). "Increased levels of CRP, HS-CRP and PCT were associated with infections, as were decreased values of TNF-α and GM-CSF." (PMID 28264059, 2017). "For example, “Proteosome degradation” and “CRP” (columns B and 4), complement (columns B and 3), and others (columns B) indicating an infection-induced response." (PMID 28243233, 2017). "CRP has been validated as a sensitive control parameter for diagnosing infections in arthroplasty and for monitoring healing processes following joint surgery." (PMID 28592300, 2017). "The percentages of individuals with acute-phase reactant values that were indicative of inflammation or infection (hs-CRP concentration >5 mg/L or α-1-antichymotrypsin concentration >0.65 g/L) were 0% in the NDNS, 15% in the NANS, and 5% in NU-AGE study." (PMID 28381473, 2017). "According to the preoperative parameters, an interesting finding was that the predictive power of individual tests, such as the CRP and synovial fluid culture, which was higher for delayed infections than for other types of PJI." (PMID 28841913, 2017). "Among the children with identified inflammation, 7/30 (23.3%) had CRP levels indicating infection and 14/43 (32.6%) were anaemic." (PMID 28441968, 2017). "C-reactive protein (CRP) is an acute phase protein reflecting the inflammatory processes in response to infection or trauma and has been well correlated with the severity of inflammatory and degenerative diseases in dogs." (PMID 29143684, 2017). "The assessment of the time of the laboratory indexes permits pointing out, in cases of infection, that the average CRP, ESR, and PCT values show a statistically significant peak compared to the average of uninfected patients' values at the same time." (PMID 29138696, 2017).